HSP90B2P (heat shock protein 90 beta family member 2, pseudogene)
Description:
Putative molecular chaperone.
Synonyms: GRP94B; GRP94P1; TRAP1; HSP; HSPCP2; TRA1P1
Gene: Processed pseudogene on chromosome 15 (99,257,632 to 99,260,015, forward strand). Ensembl gene ENSG00000259706.
Diseases named in the same sentence as HSP90B2P in open-access papers:
HSP90B2P is named in the same sentence as 223 diseases in open-access papers, as found by Europe PMC text mining. Sharing a sentence is not in itself a finding about the gene and the disease. The quoted sentences say what the papers report.
pemphigoid (1 paper, 2021). "Thus, the discovery of significant upregulation of Hsp90 genes HSP90B1, HSP90B2P, HSP90B3P in laminin-332 pemphigoid IgG treated may present a possible therapeutic approach." (PMID 34899732, 2021).
HSP90B2P also shares sentences with these, for which no sentence is quoted: tumor (251 papers); cancer (214); infection (60); breast cancer (21); diabetes (19); viral infection (19); Sepsis (17); neurodegenerative disease (15); melanoma (14); autoimmune disease (13); Autoimmunity (12); ischemia (11); glaucoma (10); Obesity (10); atherosclerosis (9); glioma (9); prostate carcinoma (9); colorectal cancer (8); lymphoma (8); bacterial infection (7); multiple myeloma (7); atrial fibrillation (6); glioblastoma (6); lung carcinoma (6); osteosarcoma (6); pancreatic cancer (6); Parkinson disease (6); rheumatoid arthritis (6); cardiovascular diseases (5); colitis (5).
A further 192 diseases each share a sentence with HSP90B2P in 5 papers or fewer.